TMEM186 (transmembrane protein 186)
Description:
As part of the MCIA complex, required for efficient assembly of the mitochondrial complex I.
Synonyms: C16orf51; DKFZP564K2062
Tractability: Antibody: UniProt predicts a signal peptide or a membrane-spanning region. PROTAC: ubiquitination databases record sites on it; its protein half-life has been measured.
Gene: Protein-coding gene on chromosome 16 (8,780,384 to 8,797,763, reverse strand). Ensembl gene ENSG00000184857.
Subcellular location: Mitochondrion inner membrane
Subcellular location (Human Protein Atlas): Cell Junctions
Pathways (Reactome):
Metabolism: Complex I biogenesis; Respiratory electron transport
Gene Ontology:
Molecular function: protein binding
Biological process: mitochondrial respiratory chain complex I assembly
Cellular component: mitochondrial complex I intermediate assembly complex; mitochondrion; mitochondrial inner membrane
Genetic constraint (gnomAD): Loss-of-function variants: 4 observed, 4.18 expected, observed/expected ratio (o/e) 0.96, 90% interval 0.46 to 1.81. That is too few expected variants to judge how well the gene tolerates losing a copy. Missense variants: 321 observed, 291.18 expected, observed/expected ratio (o/e) 1.1, 90% interval 1 to 1.21. Synonymous variants: 120 observed, 111.43 expected, observed/expected ratio (o/e) 1.08, 90% interval 0.93 to 1.25.
Homologues: Orthologues: chimpanzee TMEM186 (99% identical), macaque TMEM186 (91% identical), rabbit TMEM186 (75% identical), mouse Tmem186 (71% identical), rat Tmem186 (71% identical), guinea pig TMEM186 (71% identical), pig TMEM186 (69% identical), dog TMEM186 (68% identical), rat AABR07057217.1 (59% identical), tropical clawed frog tmem186 (37% identical), zebrafish tmem186 (34% identical), Drosophila melanogaster CG4627 (25% identical).
Diseases named in the same sentence as TMEM186 in open-access papers:
TMEM186 is named in the same sentence as 2 diseases in open-access papers, as found by Europe PMC text mining. Sharing a sentence is not in itself a finding about the gene and the disease. The quoted sentences say what the papers report.
pancreatic cancer (1 paper, 2022). "Six genes, EARS2, ARL6IP1, DNAJA3, KNOP1, RPUSD1, and TMEM186, significantly coexpressed with PALB2 in both breast and pancreatic cancer." (PMID 35779338, 2022).
cancer (1 paper, 2022). A tumor composed of atypical neoplastic, often pleomorphic cells that invade other tissues. "TBRG4, the GMR of “Q”, was upregulated in “P” (x = 1.25, WIR = 0.46) and “Q” (x = 1.73, WIR = 1.39) but not in “M”, while TMEM186, the GMR of “M”, was not regulated in any of the profiled cancer nodules." (PMID 35723406, 2022).